CD4 (CD4 molecule)
Diseases named in the same sentence as CD4 in open-access papers (continued):
Sharing a sentence is not in itself a finding about the gene and the disease.
alcohol abuse (30 papers, 2006 to 2025). The use of alcoholic beverages to excess, either on individual occasions ("binge drinking") or as a regular practice. "An age >35 years, alcohol abuse, and a decrease in the CD4 cell count were identified as risk factors for fibrosis progression in HIV/HCV-coinfected patients." (PMID 36431096, 2022). "We extracted demographic data and risk factor information, including history of alcohol abuse, smoking, CD4 count (cells/μl), and percent of follow‐up time with undetectable HIV viral load as time‐updated variables." (PMID 33094910, 2020). "Female sex, higher baseline ln(APRI), current alcohol abuse, and lower CD4 counts were significantly associated with the fibrosis progression." (PMID 28095797, 2017). "The statistical analysis included a Poisson regression to evaluate the factors associated with alcohol use disorder, and a linear regression was performed to assess the relationship between AUDIT scores and CD4 cell counts and HIV VLs." (PMID 28399823, 2017). "None of the other variables (education, body mass index [BMI], trauma sub-type, traumatic life experiences, post-traumatic stress disorder (PTSD) symptomatology, alcohol abuse, CD4 cell counts, viral load and ARV treatment) had an effect on relative LTL." (PMID 23472184, 2013). "Variables like age, sex, residence, occupation, current CD4+ T lymphocytes count, alcohol abuse, unsafe injection, tattooing, multiple sexual partner, history of sharing sharp objects, WHO stage, HAART status, HAART regimen, and HAART duration were included in the analysis." (PMID 29281718, 2017). "Cox Proportional Hazards models were used to assess the association between time-updated cocaine/crack use and progression to APRI ≥ 1.5 adjusting for age, sex, HCV duration, baseline ln(APRI), and time-updated alcohol abuse, history of other drug use and CD4+ cell count." (PMID 28095797, 2017). "Thus, this study aimed to evaluate the prevalence of alcohol abuse among PLWHA, its associated risk factors and effects on CD4 cell counts and HIV VLs in southern Brazil." (PMID 28399823, 2017). "Most importantly, the prevalence of established risk factors for advanced fibrosis or accelerated fibrosis progression (such as prior alcohol abuse, HCV-GT3, low CD4+ nadir, etc.)was comparable between patients with and without PNPLA3 risk alleles." (PMID 26599080, 2015). "Not surprisingly, alcohol abuse, CD4 cell count and baseline APRI score were predictors of progression to advanced fibrosis." (PMID 28095797, 2017). "Fourthly, all selected patients met a set of criteria for starting HCV treatment (e.g., no alcohol abuse, high CD4 cell counts, controlled HIV replication, and good treatment adherence), and this may have introduced a selection bias." (PMID 29018269, 2017). "Thirdly, all selected patients met a set of criteria for starting HCV treatment (e.g., no alcohol abuse, high CD4 cell counts, controlled HIV replication, and good treatment adherence), and this may have introduced a selection bias." (PMID 28139728, 2017). "Thirdly, the patients selected for our study were patients who met a set of criteria for starting HCV treatment (for example, no alcohol abuse, high CD4 cell counts, controlled HIV replication and good treatment adherence), and it is possible that this may have introduced a selection bias." (PMID 25367448, 2014).
cerebral toxoplasmosis (30 papers, 2010 to 2026). Infections of the brain caused by the protozoan toxoplasma gondii that primarily arise in individuals with immunologic deficiency syndromes (see also aids-related opportunistic infections). "It is possible that co-trimoxazole reduces mortality by its protective efficacy against an array of other pathogens for which HIV-infected persons with the lowest CD4 cell counts are at higher risk, such as cerebral toxoplasmosis, salmonellosis or pneumococcal disease." (PMID 22281054, 2012). "PCNSL, cerebral toxoplasmosis, and cerebral TB patients tend to have a CD4 cell count of 50 cells/mm3, below 100, and 200 cells/mm3, respectively." (PMID 39473656, 2024). "During cerebral toxoplasmosis, CD4+ and CD8+ T cells are the major source of IFN-γ in the brain, directly controlling parasite replication." (PMID 36403002, 2022). "In HIV-infected patients, seropositivity for Toxoplasma antibodies is as high as 10–40%, and it is estimated that a third of those patients will eventually progress to toxoplasma encephalitis (TE), particularly in those with CD4+ T-cell counts <50 cells/μL." (PMID 33276733, 2020). "Chronic T. gondii infection in HIV-infected individuals is a risk for development of cerebral toxoplasmosis, and congenitally transmitting the infection to the fetus in HIV-infected women, especially when CD4+T lymphocyte count falls below 100 cells/L." (PMID 28126016, 2017). "In a longitudinal clinical case study of human acquired cerebral toxoplasmosis a dual function of the Treg population was described, by simultaneous down regulation of CD4+ and activation of pathogen-specific CD8+ T lymphocytes." (PMID 28642841, 2017). "The additional analysis showed a significant protective effect of higher last CD4+ T lymphocyte count on the incidence of cerebral toxoplasmosis (HR 0.70 per 100 cell/mm3, 95 % CI 0.49–0.99)." (PMID 27001753, 2016). "Although most patients presented with headache, neurological symptoms, and fever, a small group had only aspecific symptoms such as fatigue and nausea, warranting a high index of suspicion of cerebral toxoplasmosis in all PWH with a low CD4+ T-cell and aspecific symptoms." (PMID 40985660, 2026). "This patient in our case series had a CD4+ T-cell count below 200 cells/ul, indicating severely compromised immune function, which may have been the reason for the recurrence of cerebral toxoplasmosis." (PMID 39036934, 2025). "CD4+ T-cell counts and Glasgow Coma Scale (GCS) scores were independently associated with poor outcome (modified Rankin Scale > 2) in HIV-infected patients with severe cerebral toxoplasmosis." (PMID 33276733, 2020). "Furthermore, we showed that the adoptive transfer of Ly6Chi monocytes to NFAT1−/− mice induces an increase in migration of CD4+ T cells to the CNS and controls cerebral toxoplasmosis." (PMID 31555297, 2019). "Indeed, the control of parasite in the CNS was dependent of NFAT+ monocytes, because transference of Ly6Chi monocytes from WT mice on 18 days post-infection, when the parasites is already in the CNS, controlled cerebral toxoplasmosis (decreased the number of cysts and increased the CD4+ T cells)." (PMID 31555297, 2019). "Progressive multifocal leukoencephalopathy (PML) and cerebral toxoplasmosis are severe opportunistic infections of the CNS, most commonly observed in individuals with advanced HIV/AIDS, particularly when CD4+ T-cell counts fall below 200 cells/μL." (PMID 40970056, 2025). "Cerebral toxoplasmosis is the most common opportunistic CNS infection in patients with HIV, particularly when CD4 counts fall below 100 cells/μL." (PMID 40970056, 2025). "In addition, IgM antibodies to specific antigens have been found in HIV+ patients with CD4+ >100 cells/μL who were immunized with Haemophilus influenzae Type b vaccine, and in the saliva of HIV+ patients with Toxoplasma encephalitis." (PMID 21151564, 2010).
cerebral toxoplasmosis (continued). "The difference in PCP and cerebral toxoplasmosis rates between PLHIVs with and without DM could be attributed to significant difference in CD4 counts in our study." (PMID 26287949, 2015). "In this study, we also explored the predictors of esophageal candidiasis, cerebral toxoplasmosis and PCP incidence and found that higher nadir CD4+ T lymphocyte count was highly protective among patients not under cART." (PMID 27001753, 2016). "The median CD4 cell count was 658 cells/μL (IQR 497–814); 11 patients (37%) had previously been diagnosed with an AIDS-defining infection, one of these suffering from cerebral toxoplasmosis 12 years before without clinically obvious neurological sequelae." (PMID 25815192, 2014).
renal fibrosis (30 papers, 2013 to 2025). A final common manifestation of a wide variety of chronic kidney diseases characterized by glomerulosclerosis and tubulointerstitial fibrosis. "Worsening renal fibrosis was linked with the loss of CD4+FOXP3+IL-17+ T cells in splenic single-cell suspensions." (PMID 38202170, 2023). "Progressive renal fibrosis was associated with the loss of CD4+FOXP3+IL-17+ T cells in splenic single-cell suspensions." (PMID 28693431, 2017). "In a model of kidney fibrosis, it has been suggested that basophil-derived IL-6 contributed to enhanced Th17 cell differentiation from CD4+ T cells, which contribute to renal fibrosis." (PMID 38780542, 2024). "Treatment targeting tertiary lymphoid tissue formation using anti-CD4 monoclonal antibodies has the potential to ameliorate renal fibrosis and inflammation." (PMID 38020091, 2023). "M2 macrophages in renal fibrosis were decreased by the INF-γ produced by CD8+ T cells via inhibiting the differentiation of CD4+ T cells to Th2 cells." (PMID 32921633, 2020). "A study isolated CD8+ T cells from IFN-γ KO mice and used them or WT CD8+ T cells to reconstitute CD8 KO mice and reported that IFN-γ-CD8+ T cells impair the differentiation of CD4+ T to Th2 cells and renal fibrosis." (PMID 32921633, 2020). "The infiltration of inflammatory cells, such as CD4+ T cells and macrophages, contributes to renal fibrosis following ureteric obstruction." (PMID 32921633, 2020). "Targeting TLT formation using anti-CD4 monoclonal antibodies showed the potential to ameliorate renal fibrosis and inflammation." (PMID 31804508, 2019). "One prior study has revealed the pivotal role of CD4+ T cells in renal fibrosis following ureteric obstruction." (PMID 28693431, 2017). "A previous study has reported a pivotal role of CD4+ T cells in renal fibrosis; in addition, we observed lymphocyte infiltration in kidney tissues after UUO." (PMID 28693431, 2017). "Our previous study has indicated that depletion of CD8+ T cells exacerbates CD4+ T cell-induced monocyte-to-fibroblast transition in renal fibrosis." (PMID 28025478, 2016). "Our previous study has indicated that CD8+ T cell depletion exacerbates CD4+ T cell-induced monocyte-to-fibroblast transition in renal fibrosis." (PMID 28025478, 2016). "A role of CD4+ T cells in promoting the renal fibrosis has been recently described in a mouse model of renal fibrosis induced by unilateral ureteral obstruction." (PMID 24498450, 2014). "In nonreversible UUO models others have described evidence suggesting a role for CD4+ cells in the development of renal fibrosis." (PMID 24489579, 2013). "The overexpression of BCL2L14 in CD4+ T cells might induce renal fibrosis and inflammation by regulating the differentiation and function of Tfh cells." (PMID 39080788, 2024). "H&E staining, PAS staining, immunohistochemistry, and Masson trichrome staining indicated that CD4+ Treg depletion negated the therapeutic effects of hUCMSCs-Exo@Ex-4 in glomerular injury, reduced podocytes, and renal fibrosis in DN mice, but had little impact on the effects of hUCMSCs-Exo." (PMID 39282564, 2024). "Furthermore, adaptive transfer of CD4+ type 2 T helper cell (Th2) induced more severe renal fibrosis than Th1 cell, identifying CD4+ Th2 cell as a potential target in renal fibrosis." (PMID 35699239, 2022). "Thus, researchers put forward inhibition of Th2 differentiation from CD4+ T cells as a potential therapeutic intervention for renal fibrosis." (PMID 34616308, 2021). "In fact, it is reported that CD4+ T cells contribute to the progress of renal fibrosis." (PMID 33525592, 2021). "Apparently, the present progressive renal fibrosis seen at the late-stage may be developed by the attendance of complicated cell types: presumably, cooperation between M1 macrophages and CD4+ T cells, and confrontation between M2 macrophages and CD8+ T cells." (PMID 33525592, 2021).
renal fibrosis (continued). "The number of CD4+FOXP3+ cells increased steadily, accompanied by the presence of FOXP3+IL-17+ cells, which appeared after 14 days but progressively decreased in number by the 21st day and were associated with renal fibrosis in the UUO mice." (PMID 28693431, 2017). "To explore the regulatory roles of CCR2+PIRB‐ and CCR2+PIRB+ macrophages in renal fibrosis and T‐cell inflammation, we established coculture systems with primary renal macrophages and primary fibroblasts, as well as primary renal macrophages and primary CD4+ T cells." (PMID 40995682, 2025). "However, whether renal fibrosis can be alleviated by intervening in the polarization of CD4+ T cells remains unknown." (PMID 32774389, 2020). "The binding of CD4+ T cells to MHC class II antigens would serve as an important role in immune effects and promoting renal fibrosis." (PMID 39654881, 2024). "Findings have observed the conversion of CD4+ forkhead box P3 (FOXP3)+ T regulatory (Treg) cells into T helper 17 cells (Th17), contributing to the progression of renal fibrosis." (PMID 38202170, 2023). "We have demonstrated a CD4+FOXP3+ Treg effector differentiation program that yields Th17+ cells that induce TGF-β1 mRNA expression and renal fibrosis in UUO kidneys." (PMID 28693431, 2017). "Th2 cells are the main promoter for M2 differentiation in renal fibrosis, and the absence of CD4+ T cells CD8+ T cells neither elevate M2 macrophages nor increase kidney fibrosis for UUO mice in vivo." (PMID 32921633, 2020). "The results showed that WT CD8+ T cells could reduce the differentiation of CD4+ T to Th2 cells and renal fibrosis, whereas reconstitution by IFN-γ KO CD8+ T cells did not impair fibrosis or transition of Th1 into Th2 phenotype." (PMID 34356613, 2021). "For example, PMSCs could inhibit the inflammatory response by regulating CD4+ T cell and macrophage polarization, inhibiting the inflammatory factors IFN-γ and IL-17, and upregulating the anti-inflammatory factor TGF-β and IL-10 expression to attenuate renal fibrosis in rats." (PMID 35450295, 2022). "Of note, CD4+ (but not CD8+) T cell function seems more explicit and more important in promoting renal fibrosis." (PMID 35699239, 2022). "If IFN-γ (a pro-inflammatory factor) secretion is the only function of CD8 T cells in UUO-induced renal fibrosis, then the RAG−/− mice (neither CD4 T cells nor CD8 T cells) reconstituted with CD8+ T cells would experience more mild inflammation and fibrosis compared with RAG−/− mice." (PMID 32921633, 2020).
vitamin D deficiency (30 papers, 2012 to 2026). A nutritional condition produced by a deficiency of VITAMIN D in the diet, insufficient production of vitamin D in the skin, inadequate absorption of vitamin D from the diet, or abnormal conversion of vitamin D to its bioactive metabolites. "Multimorbidity, prolonged ART exposure and vitamin D deficiency were key predictors of frailty progression, whereas CD4< 500 cells/mm3 and multimorbidity reduced the likelihood of frailty reversal." (PMID 41918468, 2026). "Daily treatment with 4000 IU of vitamin D3 significantly reduced CD4+ T-cell activation compared to treatment with 400 units of vitamin D3 in adults with vitamin D deficiency." (PMID 40276675, 2025). "In our study, some of the cases had vitamin D deficiency, even though their CD4 count was over 200 cells/mm3." (PMID 38373939, 2024). "This was consistent with our current study which revealed, Children with CD4 count of <200 cells/mm3 were at 2.16 times risk of vitamin-D Deficiency compared to those with CD4 count of >200 cells/mm3." (PMID 37215860, 2023). "Children with CD4 count of <200 cells/mm3 were at 2.16 (95%CI = 1.31, 4.26) times risk of vitamin-D Deficiency compared to those with CD4 count of >200 cells/mm3." (PMID 37215860, 2023). "Long duration of ART is associated with vitamin D insufficiency (VDI) while a low CD4 count <200/μl, advanced stages of disease and current efavirenz use were independently associated with severe VDD." (PMID 34166428, 2021). "On the other hand, children with vitamin D deficiency have lower levels of naive CD4+ T cell, CD4+ T-helper and CD8+ cytotoxic T lymphocytes." (PMID 34771540, 2021). "Individuals with vitamin D deficiency had significantly higher levels of serum GM-CSF (p = 0.04), decreased circulating activated CD4+ (p = 0.04) and CD8+ T (p = 0.04) cell frequencies than individuals with sufficient vitamin D levels." (PMID 24727903, 2014). "We show herein that severe vitamin D deficiency is associated with very low CD4 counts (<100/mm3) and inflammation in untreated HIV infection." (PMID 24058636, 2013). "Severe vitamin D deficiency was associated with low CD4 counts and increased markers of inflammation in ARV-naïve HIV-infected persons." (PMID 24058636, 2013). "In multivariate analysis, a CD4 count below 100/mm3, resistin concentration and being a smoker remained independently associated with severe vitamin D deficiency." (PMID 24058636, 2013). "In vitamin D deficiency, an opposite scenario might be observed as evidenced in our study, with high CD4+ cells and low lymphocyte B." (PMID 35681576, 2022). "After adjustment for either hsCRP, sTNFR1 or sTNFR2, the significance and magnitude of the association between severe vitamin D deficiency and having a CD4 count<100/mm3 were reduced, suggesting that these markers could in part explain this association." (PMID 24058636, 2013). "Moreover, there are studies suggesting that women’s poor CD4 recovery may be associated with vitamin D insufficiency." (PMID 36298842, 2022). "In our study, the serum CD3+, CD3+CD4+, and IgA levels in neonates with vitamin D insufficiency were lower." (PMID 35722480, 2022). "Vitamin D insufficiency and deficiency were prevalent in this U.S. HIV cohort with high CD4 cell counts and high levels of viral suppression." (PMID 28464004, 2017). "HIV-infected patients with vitamin D deficiency had lower CD4+ cell counts and higher HIV RNA levels compared to sufficient participants suggesting that treatment for HIV also reduced risk of vitamin D deficiency, which has been noted previously." (PMID 24756000, 2014). "Neonatal mice that had in utero and early-life vitamin D deficiency had significantly increased pulmonary CD3+CD4+T1ST2+ cells and reduced CD4+IL-10+ cells." (PMID 24943330, 2014). "Race, seasonality, overweight, nadir CD4 cell count less than 200 cell/mm3, and exposure to some ART, specially efavirenz, have been identified in other studies as risk factors for vitamin D deficiency." (PMID 24052874, 2012).
vitamin D deficiency (continued). "For example, SHAP could help identify subgroups of PLWH with specific combinations of risk factors (e.g., lower CD4 count, prolonged ART exposure, vitamin D deficiency) that render them particularly vulnerable to fragility fractures." (PMID 40160472, 2025). "Differentiation and recruitment of Th17 and IL-10 producing CD4+ T cells was not affected by vitamin D deficiency." (PMID 38567749, 2024). "The serum CD3+, CD3+CD4+, and IgA levels in neonates with vitamin D insufficiency were lower." (PMID 35722480, 2022). "However, during the follow-up period, the proportion of CD4+CD45RO+ and CD8+CD45RO+cells tended to increase in the groups with vitamin D deficiency." (PMID 31991892, 2020). "However, besides factors usually associated with vitamin D deficiency (e.g. phototype, season, region), HIV disease parameters such as a low CD4 count and exposure to antiretrovirals have been associated with low 25(OH)D levels." (PMID 24058636, 2013). "On the other hand, adjustment for resistin, IL-6, MCP-1 and TNF-α did not weaken the relationship between vitamin D deficiency and low CD4 counts." (PMID 24058636, 2013). "Vitamin D deficiency did not affect immunogenicity of DC from the ADLN, where CD11c+ cells purified from the ADLN of vitamin D-deficient or -replete mice had equivalent capacity to induce the proliferation of CD4+ cells from OVA-TCR transgenic mice (DO11.10)." (PMID 23826346, 2013).